FAM86B1 (family with sequence similarity 86 member B1 (gene/pseudogene))
Synonyms: MGC16279
Tractability: PROTAC: ubiquitination databases record sites on it.
Gene: Protein-coding gene on chromosome 8 (12,182,096 to 12,194,133, reverse strand). Ensembl gene ENSG00000186523.
Subcellular location (Human Protein Atlas): Vesicles
Gene Ontology:
Molecular function: protein-lysine N-methyltransferase activity
Cellular component: protein-containing complex
Genetic constraint (gnomAD): Loss-of-function variants: 0 observed, 4.04 expected, observed/expected ratio (o/e) 0, 90% interval 0 to 0.74. That is too few expected variants to judge how well the gene tolerates losing a copy. Missense variants: 13 observed, 68.09 expected, observed/expected ratio (o/e) 0.19, 90% interval 0.12 to 0.3. Synonymous variants: 4 observed, 25.02 expected, observed/expected ratio (o/e) 0.16, 90% interval 0.078 to 0.37.
Homologues: Orthologues: dog EEF2KMT (77% identical), mouse Eef2kmt (69% identical), rat Eef2kmt (69% identical), tropical clawed frog eef2kmt (50% identical), zebrafish eef2kmt (43% identical), Drosophila melanogaster CG7889 (26% identical), Caenorhabditis elegans R08D7.4 (26% identical). Paralogues in human: FAM86B2 (99% identical), EEF2KMT (92% identical).
Diseases named in the same sentence as FAM86B1 in open-access papers:
FAM86B1 is named in the same sentence as 1 disease in open-access papers, as found by Europe PMC text mining. Sharing a sentence is not in itself a finding about the gene and the disease. The quoted sentences say what the papers report.
cancer (1 paper, 2020). A tumor composed of atypical neoplastic, often pleomorphic cells that invade other tissues. "Some alterations in the genome such as FAM86B1 or GOLGA8A and duplication in the intron of PTPRN2 were up to three times more frequent in our cancer cases than in controls." (PMID 32577795, 2020).